WDSUB1 (WD repeat, sterile alpha motif and U-box domain containing 1)
Synonyms: WDSAM1; UBOX6; FLJ36175
Tractability: PROTAC: ubiquitination databases record sites on it.
Gene: Protein-coding gene on chromosome 2 (159,234,903 to 159,287,347, reverse strand). Ensembl gene ENSG00000196151.
Subcellular location (Human Protein Atlas): Nucleoli; Cytosol; Nucleoplasm
Gene Ontology:
Molecular function: ubiquitin-protein transferase activity
Biological process: protein ubiquitination
Genetic constraint (gnomAD): Loss-of-function variants: 47 observed, 52.82 expected, observed/expected ratio (o/e) 0.89, 90% interval 0.7 to 1.13. The upper end of that interval is the gene's LOEUF score, 1.13, which puts it in group 4 of 6, group 1 being the genes least tolerant of losing a copy. Missense variants: 513 observed, 580.35 expected, observed/expected ratio (o/e) 0.88, 90% interval 0.82 to 0.95. Synonymous variants: 194 observed, 203.58 expected, observed/expected ratio (o/e) 0.95, 90% interval 0.85 to 1.07.
Homologues: Orthologues: chimpanzee WDSUB1 (99% identical), macaque WDSUB1 (98% identical), dog WDSUB1 (92% identical), pig WDSUB1 (91% identical), guinea pig WDSUB1 (91% identical), rat Wdsub1 (84% identical), mouse Wdsub1 (82% identical), rabbit WDSUB1 (82% identical), tropical clawed frog wdsub1 (61% identical), zebrafish wdsub1 (57% identical).
Diseases named in the same sentence as WDSUB1 in open-access papers:
WDSUB1 is named in the same sentence as 2 diseases in open-access papers, as found by Europe PMC text mining. Sharing a sentence is not in itself a finding about the gene and the disease.
WDSUB1 shares sentences with these, for which no sentence is quoted: cancer (1 paper); deafness (1).